CXCL5 (C-X-C motif chemokine ligand 5)
Diseases named in the same sentence as CXCL5 in open-access papers (continued):
Sharing a sentence is not in itself a finding about the gene and the disease.
tumor (continued). "In addition, we used nude mice to detect the influence of CXCL5 on tumor metastasis in vivo." (PMID 28356111, 2017). "However, CXCL5 was only detected in nine of the 14 tumor samples." (PMID 28923105, 2017). "However, in the aggressively growing tumor cell line, receptor activity could be protected by the upregulation of the neutral ligand Cxcl5 (32-fold relative to vGPCR-3T3) that competes with the antagonist CXCL12 for receptor binding." (PMID 26871287, 2016). "Furthermore, we detected a significant clinicopathological association between CXCL5 expression and early tumor categories of CRC (P < 0.001), which did not occur for CXCL1 or CXCL6." (PMID 18578857, 2008). "CXCL5 not only promotes MDSC maintenance via GM‐CSF but also drives their recruitment into the tumor site through the CXCL5/CXCR2 axis, thereby enhancing immunosuppressive activity and tumor progression." (PMID 41532367, 2026). "Like CXCL1 and CXCL2, CXCL5 acts through the CXCR2 receptor on neutrophils, facilitating their migration toward the tumor site." (PMID 40486614, 2025). "Responders exhibited elevated expression of IL1B, CXCL5, HMGB1, and IFNGR2, indicative of an inflamed tumor microenvironment and type I/II interferon signaling." (PMID 40723289, 2025). "Responders exhibit a dominant signature characterized by IL1B, MIF, CXCL5, and HMGB1—indicating an inflamed, neutrophil-rich tumor microenvironment (TME) that is primed for antitumor immunity." (PMID 40723289, 2025). "CXCL1, CXCL5 and CXCL8 can recruit neutrophils and MDSCs and contribute to immune suppression and can also promote tumor cell migration and invasion of some tumor types." (PMID 40176808, 2025). "Tumor cells and stromal cells secrete a variety of chemokines and cytokines, including cysteine X cysteine ligands such as CXCL1, CXCL2, CXCL5, and CXCL8 (IL-8), that attract neutrophils to the tumor site." (PMID 40227814, 2025). "C-X-C chemokine receptor 2 (CXCR2), particularly the C-X-C motif chemokine ligand 5 (CXCL5)/CXCR2 axis, is also crucial in tumor lymphatic metastasis and chemoresistance." (PMID 40564091, 2025). "The cluster 6 monocytes were defined by high expression of multiple pro-tumor genes (IL1B, SERPINB2, CCL2, CXCL1, CXCL5, CXCL8, CCL3, CCL20)." (PMID 40176808, 2025). "It is also possible that inhibition of a tumor–MDSC interaction was interrupted after BRD4 inhibition, as additional tumor-secreted soluble factors, including chemokines (CCL2, CXCL3, and CXCL5), were all reduced after BRD4 inhibition in vitro." (PMID 40762981, 2025). "The maturation and antigen presentation functions of TIDCs can be seriously impeded by the high levels of VEGF, CCL2, CXCL1, and CXCL5, released by CAF-induced tumor cells." (PMID 40805183, 2025). "To validate SLC6A14 and CXCL5 at the protein level, we performed multiplex immunofluorescence on 20 patients with ICC, using panCK to annotate tumor cells." (PMID 39670859, 2025). "By inducing monocyte infiltration via SASP factors such as IL-6 and CXCL5, PAI-1 sustains an immunosuppressive TME, thereby facilitating tumor progression across a range of malignancies, including skin cancers." (PMID 41008624, 2025). "Chemokines such as CXCL12, CXCL5 and CCL2 regulate tumor metabolism and promote a metabolic shift toward enhanced glycolysis and lipid metabolism to support rapid tumor growth, even under hypoxic conditions." (PMID 40134607, 2025). "CXCL1 and CXCL5 recruit M-MDSCs, mediating immunosuppression by inhibiting CD8+ T cell infiltration, thereby promoting tumor progression." (PMID 40607438, 2025). "ELR-positive chemokines, including CXCL1, CXCL5, and CXCL8, are generally pro-tumorigenic by promoting angiogenesis and recruiting pro-tumor immune cells." (PMID 41516196, 2025).
tumor (continued). "TAMs increase the secretion of chemokine CXCL5, which not only recruits monocytes but also activates the PI3K/AKT/mTOR pathway in tumor cells, mediating therapeutic resistance and tumor cell survival." (PMID 39941714, 2025). "CXCL5 binds the chemokine receptor CXCR2 and facilitates tumor proliferation, invasion, and angiogenesis via various signaling pathways in different types of cancer." (PMID 40050422, 2025). "Numerous studies revealed that chemokines such as CXCL1, CXCL2, IL-8 (CXCL8), CXCL5, CXCL12, CCL2, and MIP-1α (CCL3) promote the infiltration of neutrophil to the tumoural microenvironment." (PMID 40852716, 2025). "CXCL5 and SLC6A14 were identified as potential MVI biomarkers and showed high expression in tumor-invasive areas." (PMID 39670859, 2025). "In another study, depletion of C-X-C motif Chemokine 5 (CXCL5 or ENA78) resulted in tumor angiogenesis inhibition, which further decreased the tumor progression and metastasis in NSCLC models." (PMID 41023740, 2025). "Concurrently, IL-17A enhances CXCL5 production in tumor cells and promotes MDSC migration at the tumor site through a CXCR2-dependent mechanism, facilitating tumor progression and immune evasion." (PMID 40558272, 2025). "This study identifies CXCL5 and SLC6A14 as key biomarkers of MVI, highlighting their roles in tumor proliferation, immune resistance, and poor clinical outcomes." (PMID 39670859, 2025). "In addition, numerous studies have revealed that the expression of CXCL5 is widely upregulated in malignant tumors, which could be responsible for the malignant phenotypes, including lymphatic metastasis, tumor angiogenesis, proliferation, migration and invasion." (PMID 40313933, 2025). "Recent studies on tumor-derived EVs show they can modulate gene expression in endothelial cells, promoting VEGF, VWF, VEGFR2, CXCL5, and CCR1 expression and enhancing endothelial cell proliferation and migration." (PMID 40141288, 2025). "For instance, in NSCLCs, the tumour cells over expressing ACKR1 internalises and immobilise the bound ligands CXCL5 and CXCL8 thereby restricting the downstream signalling for angiogenesis and metastasis." (PMID 40852716, 2025). "Mechanistically, PAI-1 promotes tumor angiogenesis by enhancing the production of pro-angiogenic mediators such as IL-23p19, VEGF-C, CXCL5, and CCL20." (PMID 41008624, 2025). "Upregulated pro-inflammatory chemokines CXCL6 and CXCL5, along with ECM-degrading enzymes MMP1 and MMP13, create a feedback loop that sustains inflammation and facilitates tumor-supportive immune infiltration." (PMID 40604111, 2025). "The directional movement of PMN-MDSCs is modulated by the release of C-X-C motif chemokines from tumor cells, including CXCL1, CXCL5, CXCL6, CXCL8, and CXCL12." (PMID 40722739, 2025). "The cancer cell chemoattractant Cxcl5, which is a powerful MDSC chemoattractant, was increased due to the reduced type I collagen in tumor stroma." (PMID 40677714, 2025). "Studies indicate that CXCL5 induction is driven by IL-17A or IL1 in the TME, endowing tumor cells with an invasive phenotype." (PMID 39670859, 2025). "Using next‐generation sequencing, we found that in tumor tissues with high CCL24 expression, iCAF markers (IL1A, IL1B, IL6, CXCL1, and CXCL5) were significantly highly expressed, indicating high infiltration of iCAFs in the TME." (PMID 40397411, 2025). "Our findings demonstrated that tumor growth was accelerated in the Sh‐vector+CCL20 group, whereas it was decelerated in the Sh‐CXCL5+PBS and Sh‐CXCL5+CCL20 groups." (PMID 40091357, 2025).
tumor (continued). "Sustained inflammatory induction causes the release of Pro-inflammatory cytokines IL-8, Il-17, G-CSF, CXCL5, and CXCL6 from tumor cells and recruitment of neutrophils from the bone marrow to the tumor area, stimulating TAN to develop NETosis." (PMID 38578317, 2024). "TAMs and TANs can be recruited into the tumor microenvironment by chemokines produced by cancer cells, such as the chemokines signaling axis CXCL1, CXCL2, CXCL5, CXCL8–CXCR2, and CXCR1." (PMID 39769501, 2024). "Activated YAP1 upregulates the secretion of IL-6 and TNF-α from tumor cells, as well as colony-stimulating factor 1-3 (CSF1-3), CXC motif chemokine ligand 5(CXCL5), PGE2, COX2, and other factors that recruit MDSCs." (PMID 38550587, 2024). "Neutrophils are recruited to the PDAC TME via multiple tumour-secreted chemokines including CXCL1, CXCL2, CXCL5, and CXCL8." (PMID 38384463, 2024). "IL-17A can selectively elevate the expression of chemokines with angiogenic properties by epithelial cells as well as tumor cells, such as CXCL1, CXCL5, CXCL6, and CXCL8." (PMID 38515019, 2024). "CXCL5 binds to its receptor, C-X-C motif chemokine receptor 2 (CXCR2), and the CXCL5/CXCR2 axis directly promotes angiogenesis, tumor growth, and metastasis via the ERK/Snail pathway or the AKT/GSK3β/β-catenin pathway." (PMID 39034411, 2024). "Blockade of the CXCL5/CXCR2 signaling axis can increase the sensitivity of immunotherapy and delay tumor progression." (PMID 39034411, 2024). "CXCL5, the ligand of CXCR2, is derived from primary tumor cells, but it is also secreted by immune cells in the TME." (PMID 37142825, 2024). "Activation of lung epithelial TLR3 by RNAs in tumor-derived exosomes via NF-kB and MAPK pathways increased the production of chemokines such as CXCL1, CXCL2, CXCL5, and CXCL12, leading to the recruitment and accumulation of neutrophils for PMN formation." (PMID 38495881, 2024). "By RT-qPCR, we revalidated the expression of CXCLs (CXCL2, CXCL3, CXCL5, CXCL10) in MB49 YAP1-Sh clones and tumor tissues from VP-treated mice bearing UCB cell–derived xenografts." (PMID 39630608, 2024). "CXCL5, the ligand of CXCR2, can mediate tumor cell migration and invasion and has many roles in colorectal cancer and cervical cancer." (PMID 38287266, 2024). "We found that the addition of MSCs to a tumor cell culture induced the expression of chemokines CXCL1, CXCL5, and CXCL13." (PMID 38182756, 2024). "Another study demonstrated that CXCL5 has the greatest increase in human PDAC and correlated with both tumour-infiltrating CD15+ granulocytes and neutrophil elastase+ (NE+) granulocytes." (PMID 38384463, 2024). "In our study, we found that CD73 in NSCLC tumor cells and CD39 in macrophages led to extracellular adenosine accumulation in TME, A2AR activation and CXCL5 secretion in macrophages." (PMID 38642131, 2024). "Among them, Macro-2 seems to be a key player in the tumor metastatic cascade, characterized by expression of SPP1, CCL18, CXCL5, CCL2, and CCL7." (PMID 38281962, 2024). "Chemokines chemokine C-C motif ligand (CCL) 9 (CCL9), CCL17, CCL20, CXCL5, CXCL9, and CXCL10 secreted by hepatocytes regulated tumor progression by acting on CD8+ T cells." (PMID 39346534, 2024). "Our findings unveiled a significant upregulation in a variety of cytokines in UPP1-overexpressing tumor cells, including TGF-β1, GM-CSF, IL-1β, IL-6, IGFBP-3, CXCL5, CCL20, and VEGF, with TGF-β1 being the most prominently elevated." (PMID 38331898, 2024). "CCL5, CXCL1, CXCL2, CXCL5, and CXCL12 are chemokines produced by senescent cells that have opposite effects on tumor development." (PMID 39007138, 2024). "Crucially, MDSCs are recruited to tumor sites via various chemokine axes, such as CCL8/CCR2, CCL5/CCR5, CXCL5/CXCR2, and CXCL12/CXCR4." (PMID 39769501, 2024).
tumor (continued). "Studies have shown that tumor necrosis factor-α activated CXCR2 ligands (CXCL1, CXCL2 and CXCL5) expressed by MSCs can effectively aggregate and migrate CXCR2+ neutrophils into tumor and significantly promote tumor metastasis." (PMID 39679363, 2024). "B cells can capture tumor antigens and activate immune cells in the initial stage of the immune response, or participate in tumor killing by secreting antibodies, such as CCL2, CXCR4, CCL5, CXCL5 and CXCL10, which trigger the activation of CD4 and CD8 T cells." (PMID 37254219, 2023). "Since there are reports that CXCL5 binds to C-X-C motif chemokine receptor 2 (CXCR2) to promote angiogenesis, tumor growth, and metastasis, we examined the role of CXCR2 in VSMC migration." (PMID 37373052, 2023). "We observed a moderate positive correlation for CXCL5, CXCL16, as well as CEA and CA 19–9 with tumor TNM stage." (PMID 37848726, 2023). "It is also known that PI3K-AKT-mTOR signaling pathway activation via CAF-derived secretion, such as through CXCL12, VCAM1, IL-22, CXCL5, HGF, and SPARC, induces tumor proliferation, migration, and stemness." (PMID 37264057, 2023). "Mo0 stimulated the release of cytokines and chemokines such as IL6, IL1A, CXCL1, CXCL5, and CCL20, which can induce monocyte recruitment to tumor." (PMID 37675100, 2023). "Similar to the results at the cellular level, here we found that mRNA nano-lantern promoted the expression of Smad4 protein in tumor tissues and induced the decline of MYC, VEGFC, and CXCL5." (PMID 36894556, 2023). "The recruitment of neutrophils into HCC tumor tissue, after G-CSF and IL-17-induced mobilization, is mediated by chemokines such as CXCL1–3 and CXCL5–8, which bind to the CXCR2 receptor in neutrophils." (PMID 38138981, 2023). "CXCL5 belongs to the CXC subfamily of chemokines and is involved in angiogenesis, tumor growth, and metastasis." (PMID 37015905, 2023). "As an example, C-X-C motif chemokine ligand 5 (CXCL5) is a tumor-secreted chemokine that draws MDSCs expressing C-X-C motif chemokine receptor 2 (CXCR2) and, in consequence, its suppression disrupts tumor development." (PMID 36260158, 2023). "The peritumoral administration of LL-37 significantly increased the expression of CXCL5, IL23A, MMP1a, and MMP9 mRNA in the tumor microenvironment." (PMID 36980564, 2023). "TANs can increase the stem cell properties in tumor cells via the miR-301b-3p/LASMP/CYLD signaling pathway, and liver CSCs can recruit more TANs into the TME by secreting high levels of CXCL5 because of the hyperactive NF-κB signaling." (PMID 36773210, 2023). "CXCL5 (epithelial neutrophil-activating peptide-78) and MMP-9 also recruit neutrophils in Hepato-Cellular Carcinoma (HCC) and promote tumor progression and metastasis." (PMID 37376417, 2023). "Tumor-derived GM-CSF, IL-6, IL-1β, TGF-β, IL-13, IFN-γ, CXCL5 have also been found to regulate MDSC accumulation and the polarization of tumor-infiltrating granulocytic MDSC (G-MDSC) toward an immunosuppressive phenotype." (PMID 38304256, 2023). "One of the mechanisms of neutrophil attraction to the TME is the secretion of CXCL1, CXCL2, CXCL5, and CXCL8 by the malignant cells and the tumor stroma." (PMID 36260158, 2023). "In severely hypoxic tumor regions of HCC, regulatory T cells (Tregs) and cDC2 can be attracted by CCL20 and CXCL5, and hepatoma cell-derived extracellular adenosine can recruit pDCs via the hypoxia-inducible factor (HIF)-1α/CD39/CD73 signaling pathway." (PMID 36773210, 2023). "Taking the acquired results, it can be suggested that the CXCL5, CEA, and CA 19–9 concentration rises with the development of tumor." (PMID 37848726, 2023). "Many stimuli have been reported in previous literature, including IFN-γ and GM-CSF, which induce neutrophils to N1 polarization for anti-tumor function, and IL-6, IL-8, CXCL2, and CXCL5, which induce neutrophils to N2 polarization for pro-tumor function." (PMID 37063892, 2023).
tumor (continued). "To further analyze the mechanisms of the tumor inhibition ability of mRNA nano-lantern, we evaluated the expression level of Smad4, downstream transcriptional regulatory genes, MYC, VEGFC, and CXCL5 in tumor tissues by Western blot." (PMID 36894556, 2023). "We also determined the correlation coefficients between the studied parameters, which confirmed that the concentration of CXCL5, CXCL16 and both tumor markers are closely related to the severity of CRC." (PMID 37848726, 2023). "Then, to examine the role of CXCL5 in CRC metastasis, we used lentivirus to downregulate CXCL5 in MC38-HOXC10 cells and developed the cecum orthotopic tumor implantation model in C57BL/6 mice." (PMID 36186898, 2022). "Further, Ziqian Li using primary murine CAFs isolated from the subcutaneous tissues and different mouse and human cell lines, stated that CXCL5 produced by CAFs leads to the expression of PD-L1 on the surface of melanoma and CRC tumor cells." (PMID 36275750, 2022). "FAPα promoted CXCL5 secretion in HSCs, which activated CXCR2 to promote the epithelial-mesenchymal transition of tumor cells and the recruitment of myeloid-derived suppressor cells." (PMID 35951441, 2022). "For instance, the pro-inflammatory cytokines IL-8, IL-17, G-CSF, CXCL5, and CXCL6 are released from tumor cells and recruit neutrophils in the bone marrow to tumor regions." (PMID 35764882, 2022). "As a member of the CXC chemokine family, CXCL5 is the ligand of CXCR2 and is not only derived from primary tumor cells but is also secreted by immune cells in the TME." (PMID 35246503, 2022). "CXCR2 and its ligands were described as having an antimetastatic role in renal cell carcinoma where CXCL5 and CXCL8 produced by tumor cells can attract neutrophils with antitumor activity." (PMID 35158948, 2022). "In this context, it has also been demonstrated that tumour-derived CXCL1 and CXCL5 influence in DC maturation, as reported in human CRC." (PMID 35406451, 2022). "CXCL5, a member of the CXC-type chemokine family, is overexpressed in many cancers and can promote tumor cell proliferation, migration and invasion." (PMID 36164607, 2022). "Lysates of MTX-treated 9464D tumors displayed a more than 2.5-fold increase of IL1a, CXCL16, FLT3L, CX3CL1 and IL1RA, and a more than 1.5-fold increase of CXCL10, CXCL5, CCL5 and CXCL9 compared to control tumor lysates." (PMID 36397148, 2022). "CXCL5, a ligand for CXCR2, involved in immune cell recruitment and promotes angiogenesis, tumor development, and metastasis." (PMID 36186898, 2022). "CXCL5 belongs to the CXC-type chemokine family, and studies showed that CXCL5 regulated the expression of FOXD1 and VEGFA and promoted tumor angiogenesis by activating the AKT/NF-κB pathway." (PMID 36286020, 2022). "CXCL5 and CCL2 released by macrophages in the tumor microenvironment can enhance tumor metastasis by interacting with their respective receptors in tumor cells." (PMID 36477408, 2022). "CAFs, in contrast, express paracrine molecules that promote tumour growth and therapy resistance, including growth factors (CTGF, EGF, and PDGF), chemokines (CXCL1, CXCL5, CXCL7, CXCL8, CXCL12, and CCL12), and cytokines (IL-6, IL-11, and LIF)." (PMID 36284087, 2022). "Its expression was increased in tumor tissues from patients with HCC when compared to controls, indicating that CXCL5 overexpression has a potential role in therapy of this type of tumor." (PMID 36012108, 2022). "Neutrophils are recruited to tumors mainly by ELR+-CXC chemokines produced by tumor cells (e.g., CXCL8, CXCL5, and CXCL6) and by neutrophils themselves (e.g., CXCL2) or by other cells of the tumor stroma." (PMID 35158948, 2022). "M1 macrophages promote beneficial anti-tumor effects by driving the Th1 response and via the secretion of TNF-α, IL-1, IL-6, IL-12, Type I IFN, CXCL1-3, CXCL5, and CXCL8-10." (PMID 35345849, 2022).